PTN (pleiotrophin)
Diseases named in the same sentence as PTN in open-access papers (continued):
Sharing a sentence is not in itself a finding about the gene and the disease.
breast carcinoma (continued). "Concurrently, when we plotted overall survival data of stage IV and LN+ breast cancer patients from The Cancer Genome Atlas (TCGA), elevated expression of PTN correlated with poor overall survival." (PMID 36828390, 2023). "Overexpression of PTN in breast cancer cells, such as MCF-7 gene enhanced angiogenesis in the rabbit corneal assay." (PMID 31879572, 2019). "PTN has been considered as a candidate angiogenic factor in breast cancer, melanoma and prostate cancer." (PMID 30427932, 2018). "We also found that the expression of PTN in breast cancer cells which were undergoing Dox treatment was significantly decreased when CDKN1A was knockdown." (PMID 30497491, 2018). "To understand the upstream mechanism of chemotherapy-driven increases in PTN expression in breast cancer, we found that the nucleoprotein CDKN1A exhibited the most upregulated expression after treatment with Dox via microarray analysis." (PMID 30497491, 2018). "Chemotherapy-driven increases in the CDKN1A/PTN/PTPRZ1 axis activate the NF-κB pathway in breast cancer cells." (PMID 30497491, 2018). "For example, in a breast cancer model, PTN overexpression stimulated remodeling of the microenvironment, tumor angiogenesis, and rapid tumor growth." (PMID 26914549, 2016). "PTN has also been shown to be an angiogenic factor during tumor growth and a promoter of invasion and metastasis in different tumor types including breast cancers." (PMID 23077670, 2012). "A role for PTN-mediated signaling through the receptor tyrosine kinase ALK as well as the receptor phosphatase PTPRz has been suggested in breast cancers." (PMID 23077670, 2012). "As mentioned in the Introduction, PTN has been shown to be a promoter of invasion and metastasis in different tumor types including breast cancers." (PMID 23077670, 2012). "The present review focuses on the functions of the angiogenic factors VEGF and PTN on immune cell infiltration and function in breast cancer." (PMID 24281102, 2010). "Pleiotrophin is elevated in sera or tumors from patients with colon, stomach, pancreatic, and breast cancer." (PMID 20738847, 2010). "Pleiotrophin (PTN) is an important angiogenic cytokine in breast cancer and is expressed at high levels in approximately 60% of human breast tumors." (PMID 24281102, 2010). "When MCF-7 human breast cancer cells were engineered to express high levels of PTN, tumor progression and angiogenesis was enhanced." (PMID 24281102, 2010). "The present review focuses on the functions of VEGF and PTN on immune cell infiltration and function in breast cancer." (PMID 24281102, 2010). "PTN is an important angiogenic cytokine in many models of breast cancer and is expressed highly by approximately 60% of primary breast tumors." (PMID 24281102, 2010). "Pleiotrophin (PTN) is a less studied but important angiogenic cytokine in the mammary tumor microenvironment." (PMID 24281102, 2010). "By integrating developmental and oncogenic perspectives, this review highlights PTN as a pivotal but underexplored factor in mammary gland physiology and breast cancer and outlines future research directions needed to translate PTN-targeted strategies into clinical benefit." (PMID 42193935, 2026). "Pleiotrophin (PTN), a heparin-binding growth factor with potent mitogenic and angiogenic activity, has emerged as a key regulator of mammary gland biology and a potential driver of breast cancer progression." (PMID 42193935, 2026). "Since PTN and PTPRZ1 are both expressed in different subtypes of breast cancer and PTN is also found in normal breast tissues, it will be interesting to investigate how the correlation of ITGB4 and PTPRZ1 contributes to luminal cancer progression and therapeutic response." (PMID 39518121, 2024). "PTN stimulates angiogenesis and promotes invasion and metastasis in breast cancer." (PMID 37484951, 2023). "However, a previous clinical study on an Asian cohort of patients showed PTN protein expression to be elevated in breast cancer patients." (PMID 36828390, 2023).
breast carcinoma (continued). "PTN was detected at a significantly higher level in breast cancer patients, suggesting it might have potential use as a diagnostic biomarker." (PMID 36828390, 2023). "Thus, PTN protein was purified for the first time from tissue culture supernatants of human breast cancer cells." (PMID 37484951, 2023). "Moreover, elevated PTN in plasma correlated significantly with metastasis and reduced survival of breast cancer patients." (PMID 36828390, 2023). "Additionally, inhibition of PTN significantly reduced lung metastasis in multiple mouse models of breast cancer." (PMID 36828390, 2023). "This suggests that changes in PTN level might be a predictor of prognosis in breast cancer patients." (PMID 36828390, 2023). "A better understanding of PTN function and regulation during mammary gland development could help to understand the role of PTN during breast cancer development and progression." (PMID 23077670, 2012). "It is tempting to speculate that PTN downregulation observed with multiparity is protective towards breast cancer, possibly by reducing the immature precursor population susceptible to malignant transformation and by expanding differentiated epithelial cells." (PMID 23077670, 2012). "The PTN protein was first purified from the supernatants of human breast cancer cells." (PMID 23077670, 2012). "Furthermore, we have seen that PTN is overexpressed in approximately 60% of human breast carcinoma and in chemically-induced rodent models where parity was seen to have a protective effect against tumorigenesis." (PMID 23077670, 2012). "Our studies of growth factors and their signal transduction connected the ALK receptor with the growth factor pleiotrophin (PTN): We had purified and characterized PTN from supernatants of human breast cancer cells and defined a signaling pathway of this protein." (PMID 23267434, 2012). "Microarray analysis has shown significantly lower expression of pleiotrophin in breast carcinomas." (PMID 16280042, 2005). "Elevated PTN expression has been shown to occur in malignant tumours with respect to normal tissue, for example in ovarian carcinoma, and in tumour cell lines such as breast carcinoma and glioblastoma." (PMID 11953815, 2002). "Pleiotrophin is a heparin-binding growth factor involved in the differentiation and proliferation of neuronal tissue during embryogenesis, and also secreted by melanoma and breast carcinoma cells." (PMID 11953815, 2002). "Therefore, we evaluated PTN expression in breast cancer patient plasma." (PMID 36828390, 2023). "Our current studies showed that the expression of PTN and its receptor PTPRZ1 in human breast cancer tissue depended on whether the patient received chemotherapy, and chemotherapy-driven increases in PTN/PTPRZ1 signalling could inhibit chemotherapy responsiveness in TNBC cells." (PMID 30497491, 2018). "In breast cancer, PTPRZ1 and PTN are highly expressed in relapsed as well as chemo-resistant TNBC, and PTPRZ1 is considered as an independent risk indicator for TNBC recurrence and metastasis." (PMID 39518121, 2024). "Thus, PTN may be a potential biomarker for breast cancer diagnosis." (PMID 33435254, 2021). "In this study, we uncovered that the protein levels of PTN and PTPRZ1 are significantly higher in human breast cancer tissue after receiving chemotherapy compared with cancer tissue from the same patient prior to chemotherapy." (PMID 30497491, 2018). "In conclusion, we have demonstrated that the expression levels of PTN and PTPRZ1 were upregulated in breast cancer tissue after chemotherapy compared to tissue before chemotherapy." (PMID 30497491, 2018). "Pleiotrophin (PTN) is a gene that has been found to be differentially expressed in various types of cancer, including hepatocellular carcinoma (HCC), oral squamous cell carcinoma (OSCC), ovarian cancer, and breast cancer (BrCa)." (PMID 39869563, 2025). "PTN was first purified from MDA-MB-231 cells, a human breast cancer cell line." (PMID 36828390, 2023).
breast carcinoma (continued). "PTN is expressed in primary breast cancers and in estrogen receptor-negative breast cancer cell lines, and is upregulated in carcinogen induced mammary carcinomas in rats." (PMID 37484951, 2023). "We then detected the expression of PTN and PTPRZ1 in different breast cancer cell lines via RT-PCR, and we found that PTN and PTPRZ1 were expressed at higher levels in the MDA-MB-231 and MDA-MB-453 TNBC cells than the other breast cancer cells, HCC-1937 and MCF-7." (PMID 30497491, 2018). "That means chemotherapy drugs may be one of the activation factors for PTN/PTPRZ1 pathway, following with an even bad chemotherapy sensitivity to these aggressive breast cancer phenotypes." (PMID 30497491, 2018). "Our studies indicated that chemotherapy-driven increases in the CDKN1A/PTN/PTPRZ1 axis play a critical role in chemoresistance, which suggests a novel strategy to enhance chemosensitivity in breast cancer cells, especially in those of the triple-negative subtype." (PMID 30497491, 2018). "The detection of PTN expression in primary breast cancers and in estrogen receptor negative breast cancer cell lines and its pro-angiogenic and pro-metastatic function make PTN a good candidate for therapeutic targeting." (PMID 23077670, 2012). "PTN mRNA expression has been shown in different estrogen receptor negative breast cancer cell lines and in primary breast cancers derived from different patients." (PMID 23077670, 2012). "Finally, when PTN was over-expressed in the mammary fat pad of MMTV-PyMT transgenic mice, a well characterized transgenic breast cancer model, angiogenesis and tumor progression was accelerated significantly." (PMID 24281102, 2010). "The PTN-RPTPβ/ζ pathway has been also reported to affect phosphorylation and/or activation of numerous targets, such as ALK, Fyn and its downstream substrate beta catenin, protein kinase C (PKC) alpha or beta through inhibition of the phosphatase activity in breast cancer." (PMID 30427932, 2018). "We demonstrated the tumour-promoting effects of PTN in breast cancer cells undergoing chemotherapy involved the upregulation of the expression of PTPRZ1, while the increased expression of PTPRZ1 could also stimulate the secretion of PTN to form a positive feedback loop in TNBC cells." (PMID 30497491, 2018).
prostate carcinoma (16 papers, 2008 to 2024). A carcinoma that arises from epithelial cells of the prostate gland. "AA patients with high levels of both TNFRSF9 and PTN in their sera had the highest risk of dying from prostate cancer." (PMID 35365620, 2022). "PTN mRNA was enriched in patient-matched normal prostate fibroblasts versus prostate cancer associated fibroblasts." (PMID 20812209, 2011). "For instance, pleiotrophin affects the susceptibility of prostate cancer cells to cisplatin." (PMID 37338527, 2023). "By 10 years, 33% of cases with high levels of both TNFRSF9 and PTN died of prostate cancer compared to only 5% of cases with low levels of one or both of these proteins, highlighting the utility of these blood markers for risk stratification of AA prostate cancer patients." (PMID 35365620, 2022). "Through the cell membrane functional complex of ανβ3 and PTPRZ1, PTN also activates xanthine oxidase to produce signaling levels of reactive oxygen species, required for PTN-induced endothelial and prostate cancer cell migration." (PMID 37175798, 2023). "In a study of men with prostate cancer, serum-based PTN was found to be a biomarker for metastatic progression." (PMID 37691636, 2023). "The two analytes PTN and TNFRSF9 remained the most predictive features besides the NCCN risk score, and the three features combined predicted prostate cancer-specific mortality with 90% accuracy." (PMID 35365620, 2022). "In prostate cancer, PTN regulates mesenchymal and epithelial proliferation, with PTN itself being regulated by the androgen receptor during prostate development." (PMID 35365620, 2022). "Forty-one candidates were all down-regulated in the first cohort of them, SPOCK3, SPON1, PTN and TGFB3 were associated with the prognosis of prostate cancer patients." (PMID 29190897, 2017). "Recent studies have found that PTN may be a serum biomarker promoting metastatic prostate cancer, and upregulation of PTN leads to the migration of prostate cancer cells." (PMID 38441550, 2024). "Down-regulation of RPTPβ/ζ expression has been shown to initiate epithelial-tomesenchymal transition and to increase experimental prostate cancer metastasis in nude mice, while the effects of PTN in prostate cancer growth have been attributed to its interaction with syndecan-3." (PMID 30427932, 2018). "PTN or pleiotrophin, the second protein marker found to be associated with lethal prostate cancer in AA men, may not have the same immune function that soluble TNFRSF9 exhibits." (PMID 35365620, 2022). "Experiments revealed that pleiotrophin (PTN), despite being known as a growth factor, inhibits EMT of prostate cancer cells by eliciting PTEN activation and Src inactivation through RPTPβ/ζ." (PMID 34884670, 2021). "Four genes (SPOCK3, SPON1, PTN and TGFB3) and a micro-RNA were selected for exploring their potential roles in the progression of prostate cancer." (PMID 29190897, 2017). "There were 24 genes that had been reported correlating with prostate cancer, among which TGFB3, PTN, ID4 were widely studied." (PMID 29190897, 2017). "We found that SPOCK3, SPON1, PTN and TGFB3 were significantly correlated with the progression-free survival (PFS) status of prostate cancer patients." (PMID 29190897, 2017). "Notably, PTN’s interaction with SDC3 triggers the activation of ERK1/2, thereby facilitating the metastasis of prostate cancer cells." (PMID 39285301, 2024). "In addition, AA prostate cancer patients with high levels (>median) of both TNFRSF9 and PTN in their blood at diagnosis had the worst prostate cancer-specific survival independent of disease status [(Adjusted HR = 3.09 (1.36, 7.03)]." (PMID 35365620, 2022). "PTN and TGFB3 were also found to influence the PFS of patients with prostate cancer." (PMID 29190897, 2017).
colorectal cancer (14 papers, 2012 to 2025). A primary or metastatic malignant neoplasm that affects the colon or rectum. "In summary, our study presents a spatial and cellular atlas of CRC using a chemically induced spontaneous colorectal cancer model, and identifies the PTN-mediated tumor progression and the diversity of CAFs within the TME." (PMID 40069574, 2025). "Moreover, pleiotrophin (PTN), a growth factor that is highly expressed in several cancers associated with poor prognosis, has been found to be modulated by luteolin in colorectal cancer (CRC) cells through the up-regulation of miR-384, which binds to PTN 3′-UTR." (PMID 34295245, 2021). "It was suggested that miR-384 augmented by luteolin targets PTN in colorectal cancer cells, suggesting that luteolin suppresses colorectal cancer metastasis, in part, via the miR-384/PTN axis." (PMID 33066509, 2020). "In colorectal cancer, PTN binds to RPTRβ/ζ and modulates β-catenin phosphorylation, which is the cause of a higher expression of VEGF-A and higher levels of vascularization." (PMID 30427932, 2018). "PTN protein expression has been demonstrated to be related to colorectal cancer differentiation and TNM stage." (PMID 30427932, 2018). "For example, PTN promotes angiogenesis by upregulating vascular endothelial growth factor in colorectal cancer." (PMID 28969035, 2017). "They include the action of miR-183 on βTrCP1 mRNA in colorectal cancer cells, the action of miR-143 on mouse pleiotrophin mRNA and the action of miR-34a on MDM4 mRNA in colon carcinoma cells." (PMID 24586143, 2014). "Similarly, in colorectal cancer cells, luteolin downregulated the pleiotrophin expressions and up regulated the miR‐384 expressions in vitro and in vivo experiments." (PMID 39830909, 2025). "Finally, to investigate the clinical relevance of our findings, we evaluate the correlations among PTN expression, stroma diversity and metastasis status in colorectal cancer samples." (PMID 40069574, 2025). "Building on our recent work demonstrating that PTN drives myCAF-to-iCAF transition in colorectal cancer, we hypothesise that PTN similarly promotes myCAF-to-iCAF reprogramming in HER2 + IBC, potentially contributing to its aggressive phenotype." (PMID 40624675, 2025). "Luteolin inhibits colorectal cancer cell metastasis by regulating the miR384/pleiotrophin axis." (PMID 35590327, 2022). "Moreover, luteolin shows anticancer potential against colorectal cancer (CRC) cells by modulating PTN via miR-384 expression suggesting that PTN may serve as a valuable candidate for therapeutic applications in CRC treatment." (PMID 38474604, 2024). "In colorectal cancer, PTN may play a role as the downstream of PRPH and promote tumor progression." (PMID 35281077, 2022). "For instance, PTN promotes the expression of vascular endothelial growth factor (VEGF) and the angiogenesis of colorectal cancer." (PMID 30427932, 2018).
osteosarcoma (14 papers, 2017 to 2025). A usually aggressive malignant bone-forming mesenchymal neoplasm, predominantly affecting adolescents and young adults. "High expression of the neurotrophic growth factor pleiotrophin, which upregulates P-gp, has been found to be linked to poor overall and disease-free survival in a retrospective study of 133 osteosarcoma patient samples." (PMID 32961800, 2020). "PTN (pleiotrophin) is a growth factor involved in proliferation and in osteosarcoma; its overexpression promotes EMT and doxorubicin resistance." (PMID 36980828, 2023). "Another group found that OIP5-AS1 increased doxorubicin resistance via sponging miR-137-3p and upregulating PTN in osteosarcoma." (PMID 35756672, 2022). "Recent studies have reported that lncRNA OIP5-AS1 is associated with doxorubicin resistance in osteosarcoma cells through the regulation of fibronectin-1 (FN1) and pleiotrophin (PTN)." (PMID 36499136, 2022). "More relevantly, pleiotrophin elevated chemoresistance to Adr in osteosarcoma cells by inducing the GSK3β/β-catenin signaling." (PMID 34516354, 2021). "Wu and colleagues reported that upregulation of P-gp by pleiotrophin promotes doxorubicin resistance while knockdown of pleiotrophin enhances chemosensitivity in osteosarcoma cell lines." (PMID 32961800, 2020). "Luteolin reverses MDR in osteosarcoma cells and may be a promising therapeutic agent for chemoresistant osteosarcoma by inhibiting the PTN/β-catenin/MDR1 signaling axis through miR-384 upregulation." (PMID 39519572, 2024). "In contrast, PTN expression was increased 3.2-fold in poor chemotherapy responders in osteosarcoma." (PMID 37107591, 2023). "Furthermore, high PTN expression has previously been shown to confer a poor prognosis in osteosarcoma." (PMID 37107591, 2023). "In osteosarcoma, for example, miR‐627‐3p inhibits cell growth and metastasis by targeting PTN." (PMID 35588441, 2022). "Furthermore, the OIP5‐AS1/miR‐137‐3p/PTN axis affects doxorubicin resistance in osteosarcoma." (PMID 35588441, 2022). "In addition, PTN expression is directly modulated by miR-384 and could also impede osteosarcoma cells multidrug resistance via PTN/b-catenin/MDR1 signaling axis suppression." (PMID 36430305, 2022). "Outgoing and incoming signalling pattern analyses indicated that signalings such as Collagen, MK, MIF, PTN and CD99 dominated the intercellular communication modes among cells within osteosarcomas." (PMID 39834330, 2025). "In osteosarcoma cells, lncRNA OIP5-AS1 is capable of binding to miR-200b-3p or miR-137-3p, resulting in the overexpression of FN1 or PTN, respectively." (PMID 36499136, 2022).